CASC11 (cancer susceptibility 11)
Synonyms: TCONS_00014535; LINC00990; CARLo-7; ENST00000518376; MYMLR; CARLO7
Gene: Long non-coding RNA gene on chromosome 8 (127,686,343 to 127,739,022, reverse strand). Ensembl gene ENSG00000249375.
Diseases named in the same sentence as CASC11 in open-access papers:
CASC11 is named in the same sentence as 30 diseases in open-access papers, as found by Europe PMC text mining. Sharing a sentence is not in itself a finding about the gene and the disease. The quoted sentences say what the papers report.
colorectal cancer (15 papers, 2017 to 2024). A primary or metastatic malignant neoplasm that affects the colon or rectum. "CASC11 has also been found to be up-regulated in colorectal cancer tissues in association with tumor dimension, serosal invasion, metastasis to lymph node, and TNM stage." (PMID 37427385, 2023). "Studies have shown that cancer susceptibility candidate 11 (CASC11), a newly discovered long non-coding RNA (lncRNA), was aberrantly overexpressed in hepatic carcinoma, gastric cancer and colorectal cancer." (PMID 31255182, 2019). "Among them, CASC11 has been found to function as an oncogenic lncRNA in various kinds of human cancers, including colorectal cancer, gastric cancer, bladder cancer, ovarian cancer, and HCC." (PMID 37552314, 2023). "CASC11 can also enhance proliferation of colorectal cancer cells through targeting hnRNP-K and activating WNT/β-catenin signaling." (PMID 37427385, 2023). "Similar to bladder cancer, CASC11 has been shown to sponge certain miRNAs in colorectal cancer cell." (PMID 37427385, 2023). "Experiments in colorectal cancer cells have shown the ability of CASC11 to bind with miR-646 and miR-381-3p in the cytoplasm." (PMID 37427385, 2023). "In the current study, we aimed to evaluate the expression as well as the possible relationship among MYC, PVT1, and CASC11 in colorectal cancer." (PMID 36052265, 2022). "LncRNA CASC11 was demonstrated to target hnRNP K to activate WNT/β-catenin signaling in colorectal cancer cells." (PMID 34707498, 2021). "We previously reported that the long non-coding RNA (lncRNA) CASC11 promotes colorectal cancer (CRC) progression as an oncogene by binding to HNRNPK." (PMID 33937069, 2021). "LncRNA CASC11 has shown to be an important oncogene in many kinds of cancers such as colorectal cancer, gastric cancer, osteosarcoma, ovarian squamous cell carcinoma, and lung cancer." (PMID 33252856, 2020). "Based on a knockdown study, CASC11 is thought to have a promoting role in colorectal cancer growth and metastasis." (PMID 31379917, 2019). "The upregulation of CASC11 was reported to participated in the proliferation, migration and invasion of tumor cells in hepatic carcinoma, gastric and colorectal cancer." (PMID 31255182, 2019). "Besides, CASC11 silencing has reduced Ki-67 expression and suppressed metastases of colorectal cancer to lung and liver." (PMID 37427385, 2023). "Similarly, experiments in animal models of colorectal cancer have shown the role of CASC11 in enhancement of tumor growth." (PMID 37427385, 2023). "Evidence indicates that other members of the CASC family (CASC2, CASC11, CASC9) could be associated with enhanced or reduced proliferation, invasion, and apoptosis in cervical and colorectal cancers." (PMID 35887085, 2022). "In addition, numerous colorectal cancer associated lncRNAs, such as CCAT6 (MYCLo-2), CASC8 (CARLo-1), CASC21 (CARLo-2), PRNCR1 (CARLo-3), PCAT2 (CARLo-4), and CASC11 (CARLo-7), have been identified." (PMID 30441811, 2018). "Besides, miR-646 and miR-381-3p inhibitors could reverse the inhibitory effects of CASC11 knock out on proliferation of colorectal cancer cells." (PMID 37427385, 2023). "Additionally, there have already been several researches uncovering the intermediating effects of hnRNPK between lncRNAs and β-catenin, and in detail, lncRNA CASC11 interacted with hnRNPK and then activated Wnt/β-catenin signaling to augment the growth and metastasis in colorectal cancer." (PMID 38111678, 2023). "In this study, gene expression analyses indicated that the expression of some PVT1 spliced linear transcripts, CircPVT1, CASC11, and MYC is increased in colorectal cancer (CRC)." (PMID 36052265, 2022). "To elucidate the role of PVT1, CASC11, and MYC in CRC, we assessed the expression levels of these genes using qRT-PCR for cancerous and adjacent normal tissues from colorectal cancer patients." (PMID 36052265, 2022).
colorectal cancer (continued). "Additionally, long non-coding RNA CASC11 interacts with hnRNP-K and activates the WNT/β-catenin pathway to promote growth and metastasis in colorectal cancer." (PMID 29340086, 2017).
gastric cancer (10 papers, 2019 to 2025). A primary or metastatic malignant neoplasm involving the stomach. "CASC11 can also promote malignant features in gastric cancer through regulation of cell cycle pathway." (PMID 37427385, 2023). "Another study in gastric cancer cells has shown that expression of CASC11 is induced by overexpression of LINC01116." (PMID 37427385, 2023). "In gastric cancer tissues, expression of CASC11 has been found to be increased parallel with up-regulation of another lncRNA, namely, LINC01116." (PMID 37427385, 2023). "For instance, CASC11 is highly expressed in gastric cancer tissues and is involved in the promotion of the growth, invasion, and metastasis of gastric cancer via the CASC11/miR-340-5p/CDK1 axis." (PMID 33937069, 2021). "According to current studies, CASC11 can act as a critical tumour promoter in various tumours, such as gastric cancer, liver cancer glioma and CRC." (PMID 33937069, 2021). "For instance, upregulated lncRNA CASC11 in gastric cancer was demonstrated to facilitate cell proliferation, inhibit cell apoptosis, and block cell cycle and therefore promote the development of gastric cancer." (PMID 40069867, 2025). "It is known that lncRNA CASC11 promotes the development of gastric cancer." (PMID 30910841, 2019). "It has been reported that lncRNA CASC11 promotes colorectal cancer and gastric cancer." (PMID 30910841, 2019). "Recently, it has been reported that CASC11 might play a role in the carcinogenesis of CRC, gastric cancer, hepatocellular carcinoma (HCC), and cervical cancer (CC) via activating Wnt/β-catenin and PI3K/AKT signaling pathways." (PMID 36052265, 2022).
hepatocellular carcinoma (10 papers, 2019 to 2023). A malignant tumor that arises from hepatocytes. "Another lncRNA located in this region, cancer susceptibility 11 (CASC11), has been found to promote gastric, colorectal, and hepatocellular cancers." (PMID 36052265, 2022). "Among them, cancer susceptibility candidate 11 (CASC11) has displayed an impressively essential role in various kinds of cancers including hepatocellular carcinoma (HCC)." (PMID 33252856, 2020). "Our study was carried out to investigate the possible involvement of ncRNA CASC11 in hepatocellular carcinoma (HCC)." (PMID 30910841, 2019). "Up to now, two studies have reported that LncRNA CASC11 and LncRNA GAS5-AS1 can mediate the m6A modification through affecting ALKBH5 in hepatocellular carcinoma and cervical cancer, respectively." (PMID 37365581, 2023). "Moreover, LncRNA CASC11 also interfered the interaction between UBE2T mRNA and YTHDF2, thereby influencing proliferation and metastasis of hepatocellular carcinoma cells." (PMID 37365581, 2023). "In detail, LncRNA CASC11 is involved in the regulation of cell proliferation, migration as well as invasion through the upregulation of Ubiquitin-conjugating enzyme E2T (UBE2T) in an m6A-dependent manner in hepatocellular carcinoma." (PMID 37365581, 2023). "CASC11 is an oncogenic lncRNA, which involved with influencing tumor cell stemness, cancer cell proliferation and epithelial-mesenchymal transition (EMT) in CRC, small cell lung cancer, bladder cancer, prostate cancer, hepatocellular carcinoma (HCC)." (PMID 31442207, 2019).
bladder cancer (8 papers, 2019 to 2023). "Plasma levels of CASC11 has been found to be up-regulated, while levels of miR‐150 has been down-regulated in early stages bladder cancer compared with their levels in healthy controls." (PMID 37427385, 2023). "Cumulatively, CASC11 has a role in regulation of proliferation of bladder cancer cells through modulation of miR‐150 levels." (PMID 37427385, 2023). "For example, lncRNA CASC11 promotes the proliferation of bladder cancer cells by sponging miRNA-150, and exosomal lncRNA LNMAT2 promotes lymphatic metastasis in bladder cancer." (PMID 36003338, 2022). "Overexpression of lncRNA CASC11 promotes bladder cancer cell proliferation via inhibition of miR-150 expression." (PMID 33344462, 2020). "In bladder cancer cell lines, upregulation of CASC11 has led to suppression of miR‐150 expression." (PMID 37427385, 2023). "lncRNA CASC11 promoted bladder cancer cell proliferation through miRNA-150." (PMID 39280890, 2022). "Moreover, CASC11 expression has been inversely correlated with miR‐150 expression in patients with bladder cancer but not in cancer-free subjects." (PMID 37427385, 2023). "Conversely, upregulation of CASC11 could not affect migration and invasion of bladder cancer cells." (PMID 37427385, 2023).
prostate carcinoma (8 papers, 2018 to 2025). A carcinoma that arises from epithelial cells of the prostate gland. "The EPIN of CASC11 promoter is also affected by variant rs10090154, the same well known variant associated with risk of developing prostate carcinoma that we introduced with MYC EPIN42,43." (PMID 38057321, 2023). "For example, miR-150 served as the direct target of lncRNA CASC11 during the promoted effect of lncRNA CASC11 on prostate cancer." (PMID 35412954, 2022). "Interestingly, CASC11 is known to enhance prostate cancer aggressiveness and is regulated by C-MYC44, while being close to the MYC gene on chromosome 8." (PMID 38057321, 2023). "Ectopic overexpression of CASC11 from the CASC gene family significantly enhances the proliferation, migration, and colony-forming ability of DU145, LNCaP, and PC3 prostate cancer (PCa) cells." (PMID 40689207, 2025). "This overexpression of CASC11 leads to the inhibition of miR-145 and the overexpression of IGF1R, resulting in the activation of the PI3K/AKT/mTOR signaling pathway, which influences the malignant phenotype of prostate cancer cells." (PMID 40689207, 2025). "Several other genes and ncRNAs at 8q24, such as POU5F1B (previously thought to be a pseudogene), PRNCR1, CASC11 and CCAT2, have also been shown to be overexpressed in prostate cancer and may also play a role in the development or progression of prostate cancer." (PMID 33374332, 2020).
lung cancer (5 papers, 2020 to 2025). A malignant neoplasm involving the lung. "Experimental evidence suggests that CASC11 facilitates the progression of lung cancer by interacting with microRNA-302, increasing the expression of CDK1." (PMID 40303981, 2025). "FOXO3a has been shown to bind to the promoter of lncRNA CASC11, thereby promoting the tumorigenesis of non‐small cell lung cancer." (PMID 32558131, 2020).
atherosclerosis (4 papers, 2020 to 2025). A disease characterized by the build-up of fatty material and calcium deposition in the arterial wall resulting in partial or complete occlusion of the arterial lumen. "LncRNAs, including H19, TUG1, MIAT, and CASC11, can be detected in serum and could serve as potential diagnostic markers for atherosclerosis." (PMID 40941416, 2025). "The level of some lncRNAs, such as CASC11, H19, TUG1, and MIAT, can be analysed in serum samples as potential diagnostic markers for atherosclerosis." (PMID 39273193, 2024). "CASC11 is an lncRNA participating in the pathoetiology of diverse cancers as well as atherosclerosis, coronary artery disease and postmenopausal osteoporosis." (PMID 37427385, 2023). "Accordingly, the downregulation of CASC11 in the plasma of atherosclerosis patients was found to promote VSMC proliferation and the expression of IL-9, which contributes to atherosclerosis." (PMID 31998442, 2020). "Deregulation of lncRNAs, including H19, TUG1, GAS5, RAPIA, MIAT, CASC11, NEXN-AS1, and lnc00113, has been observed in individuals with atherosclerosis." (PMID 40941416, 2025). "The deregulation of many lncRNAs, including RAPIA, H19, CASC11, GAS5, TUG1, MIAT, lnc00113, and NEXN-AS1, has been observed in patients with atherosclerosis." (PMID 39273193, 2024).
cervical cancer (3 papers, 2019 to 2023). A primary or metastatic malignant neoplasm involving the cervix. "In patients with cervical cancer, CASC11 expression has been positively associated with tumor size and FIGO staging and negatively correlated to the survival of patients." (PMID 37427385, 2023). "Kaplan–Meier test showed that high level of CASC11 was significantly associated with the low survival rate for cervical cancer patients." (PMID 31255182, 2019). "Our study demonstrated that CASC11 promoted the cervical cancer progression by activating Wnt/β-catenin signaling pathway for the first time, which provides a new target or a potential diagnostic biomarker of the treatment for cervical cancer." (PMID 31255182, 2019). "Mechanistically, CASC11 promotes migration and invasion of cervical cancer cells through inducing activity of Wnt/β-catenin signaling." (PMID 37427385, 2023). "In animal models of cervical cancer, CASC11 silencing has led to reduction of tumor volume and weight and downregulation of β-catenin." (PMID 37427385, 2023). "We further measured the RNA levels of CASC11 in cervical cancer cells finding that the relative expression of CASC11 in HeLa, CaSki, SiHa, C-33A and MS751 were remarkably higher than that in the normal ectocervical cells HEKn." (PMID 31255182, 2019). "The present study was aimed to investigate the relationship between lncRNA CASC11 and cervical cancer and further explore the mechanism of CASC11 effect on cervical cancer progression." (PMID 31255182, 2019). "In the present study, we discovered that CASC11, the expression of which was positively associated with the tumor size and the FIGO staging, was up-regulated in the cervical cancer tissues and cell lines." (PMID 31255182, 2019). "CASC11 expression was detected by RT-qPCR analysis in HEKn and cervical cancer cell lines (HeLa, Caski, SiHa, C-33A and MS751)." (PMID 31255182, 2019). "Quantitative real-time polymerase chain reaction (RT-qPCR) was used to detect the expressions of CASC11 in cancerous and adjacent normal tissues of patients with cervical cancer as well as in cell lines." (PMID 31255182, 2019). "Further study showed that CASC11 promoted the migration and invasion of cervical cancer cells by activating Wnt/β-catenin signaling pathway and silencing CASC11 inhibited the tumor growth in vivo." (PMID 31255182, 2019). "Kaplan–Meier test showed CASC11 expression was negatively related to the cervical cancer patients’ survival rate." (PMID 31255182, 2019). "Furthermore, among the cervical cancer cell lines, HeLa cells showed the highest expression of CASC11 and CaSki cells displayed the lowest CASC11 level." (PMID 31255182, 2019). "We discovered that CASC11, the expression of which was positively associated with the tumor size and the FIGO staging and negatively related to the patients’ survival rate, was up-regulated in the cervical cancer tissues and cell lines." (PMID 31255182, 2019). "CASC11 promoted the migration and invasion of cervical cancer cells." (PMID 31255182, 2019). "Therefore, next we will investigate the direct targets of CASC11 in cervical cancers and explore its mechanism comprehensively." (PMID 31255182, 2019). "Therefore, we hypothesized that CASC11 has a similar function for cervical cancer and discovered that CASC11 promoted the proliferation, metastasis and invasion of cervical cancer cells through Wnt/β-catenin signaling pathway." (PMID 31255182, 2019). "In the present study, we explored the relationship between lncRNA CASC11 and cervical cancer finding that high expression of lncRNA CASC11 promoted the growth and metastasis of cervical cancer through Wnt/β-catenin pathway, which provided a new target for the treatment of cervical cancer." (PMID 31255182, 2019). "However, no one has yet reported the effects of lncRNA CASC11 in cervical cancer." (PMID 31255182, 2019).
lymph node metastasis (3 papers, 2019 to 2024). "The age, menopause, lymph node metastasis and lymphatic vascular space invasion of patients have little effect on CASC11 expression, but which was positively correlated with the FIGO stage and the tumor size." (PMID 31255182, 2019). "Higher expression of CASC11 was associated with TNM stage and lymph node metastasis." (PMID 33330110, 2020).
postmenopausal osteoporosis (3 papers, 2021 to 2025). Metabolic disorder associated with fractures of the femoral neck, vertebrae, and distal forearm. "For instance, lncRNA CASC11 is up-regulated in the postmenopausal osteoporosis and is associated with TNF-α." (PMID 34583640, 2021). "LncRNA CASC11 can drive the development of postmenopausal osteoporosis by upregulating tumor necrosis factor-α levels." (PMID 40292220, 2025).
endometrial carcinoma (2 papers, 2021 to 2024). A malignant tumor arising from the epithelium that lines the cavity of the uterine body. "However, different target genes were observed as well, like CASC8, CASC11, and LINC01137 were only detected in EOC cells, indicating the different roles of these genes in tumorigenesis between endometrial cancer and EOC." (PMID 33815481, 2021).
glioma (2 papers, 2021 to 2023). A benign or malignant brain and spinal cord tumor that arises from glial cells (astrocytes, oligodendrocytes, ependymal cells). "In the glioma cells, CASC11 has been demonstrated to sponge miR-498 and increase expression of FOXK1." (PMID 37427385, 2023). "Other studies in animal models of glioma, hepatocellular carcinoma, lung cancer and prostate cancer support oncogenic role of CASC11." (PMID 37427385, 2023).
liver cancer (2 papers, 2021 to 2024). An epithelial or non-epithelial malignant neoplasm that arises from the liver. "In addition, CASC11 is highly expressed in liver cancer cells and promotes liver cancer progression by activating the PI3K/AKT pathway." (PMID 33937069, 2021).
neuroblastoma (2 papers, 2022 to 2024). Neuroblastoma (NB) is the most common solid, extracranial childhood tumor. "Elevated CASC11 expression levels have been found in neonatal neuroblastoma tissue and correlate positively with poor clinical outcomes." (PMID 38891878, 2024). "Conversely, the siRNA-mediated silencing of CASC11 reduces the proliferation and invasiveness of neuroblastoma cells." (PMID 38891878, 2024). "The study determined the relationship between miR‐676‐3p, CASC11, and NOL4L based on bioinformatics tools and found that high expression of NOL4L reversed the effects of CASC11 on neonatal neuroblastoma, including inhibition of proliferation or proliferation." (PMID 35592755, 2022).
non-small cell lung carcinoma (2 papers, 2021 to 2024). A group of at least three distinct histological types of lung cancer, including non-small cell squamous cell carcinoma, adenocarcinoma, and large cell carcinoma. "Moreover, CASC11 targets the miR-498/FOXO3 axis and accelerates the proliferation and cell cycle progression of non-small-cell lung cancer." (PMID 33937069, 2021).
osteoporosis (2 papers, 2024 to 2025). A condition of reduced bone mass, with decreased cortical thickness and a decrease in the number and size of the trabeculae of cancellous bone (but normal chemical composition), resulting in increased fracture incidence. "The increased expression of CASC11, a crucial diagnostic marker for osteoporosis, was associated with an extended treatment duration and a high recurrence rate." (PMID 41158629, 2025).
pancreatic cancer (1 paper, 2021). "Interestingly, a SNP located in CASC11 was involved in 70% of the SNP–SNP interaction pairs significantly associated with pancreatic cancer risk, with the most common genetic interaction being between PVT1 and CASC11." (PMID 33499210, 2021).